CLMP (CXADR like cell adhesion molecule)
Description:
May be involved in the cell-cell adhesion. May play a role in adipocyte differentiation and development of obesity. Is required for normal small intestine development.
Synonyms: ACAM; ASAM; FLJ22415; CSBM; CSBS
Tractability: Antibody: UniProt places it where antibodies can reach, with high confidence; UniProt predicts a signal peptide or a membrane-spanning region; its Gene Ontology location is reachable by antibodies, with medium confidence. PROTAC: ubiquitination databases record sites on it; its protein half-life has been measured.
Gene: Protein-coding gene on chromosome 11 (123,069,853 to 123,196,697, reverse strand). Ensembl gene ENSG00000166250.
Subcellular location: Cell junction, tight junction; Cell membrane
Gene Ontology:
Molecular function: protein binding
Biological process: digestive tract development; postsynaptic modulation of chemical synaptic transmission
Cellular component: bicellular tight junction; cell surface; cytoplasmic microtubule; cell junction; membrane; plasma membrane; postsynaptic membrane
Genetic constraint (gnomAD): Loss-of-function variants: 27 observed, 47.03 expected, observed/expected ratio (o/e) 0.57, 90% interval 0.42 to 0.79. The upper end of that interval is the gene's LOEUF score, 0.79, which puts it in group 3 of 6, group 1 being the genes least tolerant of losing a copy. Missense variants: 403 observed, 468.18 expected, observed/expected ratio (o/e) 0.86, 90% interval 0.79 to 0.94. Synonymous variants: 167 observed, 179.25 expected, observed/expected ratio (o/e) 0.93, 90% interval 0.82 to 1.06.
Homologues: Orthologues: macaque CLMP (99% identical), chimpanzee CLMP (98% identical), mouse Clmp (93% identical), rat Clmp (93% identical), pig CLMP (92% identical), guinea pig CLMP (92% identical), dog CLMP (90% identical), zebrafish si:dkey-22i16.9 (18% identical), zebrafish jam2b (15% identical), zebrafish jam2a (13% identical). Paralogues in human: CXADR (28% identical), IGSF11 (27% identical), ESAM (25% identical), VSIG8 (23% identical), VSIG1 (23% identical), GPA33 (22% identical), VSIG2 (20% identical), MXRA8 (19% identical), JAM3 (16% identical), JAM2 (15% identical), F11R (14% identical), MUC15 (13% identical), and 2 more.
Diseases named in the same sentence as CLMP in open-access papers:
CLMP is named in the same sentence as 28 diseases in open-access papers, as found by Europe PMC text mining. Sharing a sentence is not in itself a finding about the gene and the disease. The quoted sentences say what the papers report.
congenital short bowel syndrome (5 papers, 2013 to 2023). Congenital short bowel syndrome is a rare intestinal disorder of neonates of unknown etiology. "Loss-of-function mutations in CLMP were identified in patients with Congenital Short Bowel Syndrome (CSBS)." (PMID 23460781, 2013). "More research is needed to better understand the function of CLMP and why loss-of-function mutations in CLMP cause Congenital Short Bowel Syndrome." (PMID 23460781, 2013). "Mutations of CLMP are associated with congenital short-bowel syndrome." (PMID 34439758, 2021). "Loss-of-function mutations in CLMP have been found in patients with Congenital Short Bowel Syndrome (CSBS), suggesting that its encoded protein plays a major role in intestinal development." (PMID 23460781, 2013). "The immunoglobulin-like cell adhesion molecule CLMP is a member of the CAR family of cell adhesion proteins and is implicated in human congenital short-bowel syndrome (CSBS)." (PMID 36982793, 2023). "CAR-like membrane protein (CLMP), an immunoglobulin cell adhesion molecule (IgCAM), has been implicated in congenital short-bowel syndrome in humans, a condition with high mortality for which there is currently no cure." (PMID 29361518, 2018).
hydronephrosis (3 papers, 2018 to 2023). Collection of urine in the renal pelvis that results in dilatation of the renal pelvis and calyces. "CLMP deficiency also provoked malrotation of the short bowel and, in addition, a severe bilateral hydronephrosis due to an uncoordinated contraction of the ureter." (PMID 29361518, 2018). "Hydronephrosis in CLMP-deficient mice is therefore likely a secondary consequence of the lack of urine transport and back pressure from the fluid-filled ureter." (PMID 29361518, 2018). "Thus, in addition to impaired intestinal motility, CLMP-deficient mice also have severe bilateral hydronephrosis." (PMID 35111702, 2021). "In addition to the impaired intestinal motility, mature CLMP-deficient mice develop severe bilateral hydronephrosis, which involves dilatation and distension of the renal pelvis and calyces." (PMID 29361518, 2018). "Consequently, insufficient transport of chyme and urine caused a fatal delay to thrive, a high rate of mortality, and provoked a severe hydronephrosis in CLMP knockouts." (PMID 29361518, 2018). "Therefore, hydronephrosis in CLMP-deficient mice is driven by a lack of urine transport from the kidney to the bladder." (PMID 36982793, 2023). "In addition to the intestinal deficits, CLMP-deficient mice that survived past weaning age developed a severe bilateral hydronephrosis that has not been described in human CSBS patients or might have been overlooked due to their early lethality." (PMID 29361518, 2018).
myocardial infarction (3 papers, 2021 to 2025). Gross necrosis of the myocardium, as a result of interruption of the blood supply to the area, as in coronary thrombosis. "It was recently reported that CLMP is highly upregulated in murine cardiac fibroblasts—but less so in myogenic cells—in the injured zone of the heart after a myocardial infarction." (PMID 36982793, 2023). "In this same study, mice expressing only 50% of wild-type CLMP levels exhibited more severe heart dysfunction than their wild-type peers after myocardial infarction, as demonstrated by echocardiography." (PMID 36982793, 2023). "CLMP is involved in inflammatory response of cardiac fibroblasts during myocardial infarction." (PMID 39739031, 2025). "Studies of sepsis-related cardiac dysfunction have shown that CXADR-like membrane protein (CLMP) was involved in myocardial cell pyroptosis after myocardial infarction in mice, but knockdown of CLMP expression enhanced myocardial cell pyroptosis and aggravated myocardial injury." (PMID 34305952, 2021).
Obesity (3 papers, 2020 to 2023). Accumulation of substantial excess body fat. "The authors of the study concluded that the overexpression of CLMP (ACAM) in mice protects from obesity and diabetes." (PMID 36982793, 2023).
colon cancer (2 papers, 2023 to 2025). "We found targets not previously studied in STS like GPC6, a member of the glypican family which is pathogenic in sarcomas, or CLMP, described as tumor suppressor in colon cancer." (PMID 40814001, 2025). "CLMP was the central immune-related gene in colon cancer, associated with the inflammatory response, KRAS signaling pathway, and T-cell infiltration." (PMID 37588985, 2023).
malnutrition (2 papers, 2018 to 2023). Inadequate nutrition resulting from poor diet, malabsorption, or abnormal nutrient distribution. "Taken together, our data above suggest that the decreased motility and severe dilation of the small intestine might explain the malnutrition and a severe delay to thrive of CLMP-deficient mice." (PMID 29361518, 2018).
acute lymphoblastic leukemia (1 paper, 2024). Leukemia with an acute onset, characterized by the presence of lymphoblasts in the bone marrow and the peripheral blood. "CLMP was linked to T-cell lymphomas, acute lymphoblastic leukemia, chronic myeloid leukemia, mesothelioma, malignant neoplasm of the rectosigmoid junction, and stomach cancer." (PMID 39003418, 2024).
cerebral atherosclerosis (1 paper, 2023). Atherosclerosis of the cerebral vasculature. "Probably, CLMP plays a substantial role in the formation of cerebral atherosclerosis since it encodes a type I transmembrane protein that is found in junctional complexes between endothelial and epithelial cells." (PMID 37372351, 2023).
epilepsy (1 paper, 2020). A brain disorder characterized by episodes of abnormally increased neuronal discharge resulting in transient episodes of sensory or motor neurological dysfunction, or psychic dysfunction. "In addition, synaptic adhesion molecules have been increasingly associated with epilepsy, suggesting the possible association of CLMP with epilepsy as well." (PMID 33408624, 2020).
Myocardial fibrosis (1 paper, 2020). "The Clmp+/− mice showed more serious myocardial fibrosis and ventricular dysfunction post‐MI than wild‐type (Clmp+/+) mice, indicating a protective effect of the fibroblast‐expressed CLMP against MI‐induced heart damage." (PMID 33084169, 2020). "Further studies indicated that the MI‐elevated CLMP might serve as a brake on excessive pyroptotic and inflammatory response of CFs, and thus prevent the MI heart from serious myocardial fibrosis and ventricular dysfunction." (PMID 33084169, 2020).
type 2 diabetes (1 paper, 2023). "CLMP was also independently identified in a screen for genes upregulated in visceral adipose tissue in a rat model of type 2 diabetes and termed adipocyte cell adhesion molecule (ACAM)." (PMID 36982793, 2023). "CLMP (ACAM) was also identified in a screen for genes upregulated in visceral adipose tissue in a rat model of type 2 diabetes, and is abundantly expressed on the cell surface of mature adipocytes." (PMID 36982793, 2023).
tumor (7 papers, 2020 to 2026). "CLMP has been known as a new component of epithelial tight junctions, which support the function of hub genes in tumor cell metastasis." (PMID 32859214, 2020). "CLMP regulates colon epithelial cell proliferation and helps prevent tumor growth." (PMID 40257955, 2025). "Four of 13 overlapped markers (MXRA8, CLMP, VCAN and FBLN1) are involved in cell adhesion and tumor metastasis, suggesting that dysfunctions in cell adhesion pathways could lead to anti-PD-1 resistance associated by RIPK1 and AXL." (PMID 36518525, 2022).
cancer (3 papers, 2022 to 2025). A tumor composed of atypical neoplastic, often pleomorphic cells that invade other tissues. "We also validated the LC substrate candidates CLMP, ICAM1, PCDH17, as well as the cancer-related GPNMB and TIMD4 as substrates." (PMID 40593564, 2025). "For many targets like CLMP, PDGFRB, NOTCH2, and GPC6, TCGA SARC samples had the highest median expression compared with other cancer types in the TCGA Pan-Cancer Atlas." (PMID 40814001, 2025).
ischaemic heart diseases (1 paper, 2020). "Despite its abundant expression in heart tissues, little is known about the biological functions of CLMP in heart development and the pathological process of cardiac diseases." (PMID 33084169, 2020).
CLMP also shares sentences with these, for which no sentence is quoted: diabetes (2 papers); short bowel syndrome (2); carotid atherosclerosis (1); chronic myeloid leukemia (1); endometrial cancer (1); malignant neoplasm of the rectosigmoid (1); mesothelioma (1); multiple sclerosis (1); myeloma (1); sarcoma (1); Sepsis (1); stomach cancer (1); T-cell lymphomas (1); temporal lobe epilepsy (1).